CCND1 (cyclin D1)
Diseases named in the same sentence as CCND1 in open-access papers (continued):
Sharing a sentence is not in itself a finding about the gene and the disease.
cancer (continued). "This study supports that TY-NS-B suppresses the proliferation of cancer cells, and downregulation of cyclin D1 may play a role in TY-NS-B-induced anti-cancer activity." (PMID 29925351, 2018). "Moreover, these extracts increased the expression level of Bax mRNA in PANC-1 cell lines whereas the cyclin D1 expression was decreased in the treated cancer cells." (PMID 30607339, 2018). "Thus, the regulation of cyclin D1 expression has been thought for the potential molecular target of the cancer treatment." (PMID 29925351, 2018). "Cyclin D1 is a proto-oncogene that is upregulated in various cancers and plays an important role in transition of G1 to S phase progression by binding to cyclin-dependent kinases such as CKD2 and CDK4 that promotes cell cycle through inhibition of phosphorylation of retinoblastoma protein (Rb)." (PMID 29515762, 2018). "Through this positive feedback loop, PIN1 may contribute to the G1 checkpoint progression through phosphorylation of Rb and over-expression of PIN1 and cyclin D1 in cancers." (PMID 30534074, 2018). "Interestingly, the BCL-2-related apoptosis pathway and cyclin D1-related pathway were reported to be the targets of miR-34c in cancer." (PMID 29654165, 2018). "However, an insufficient dose of L-ascorbic acid stimulates cancer cell proliferation, which is mediated by cyclin D1." (PMID 30054560, 2018). "SHetA2 reduced cyclin D1 to greater extents in cancer compared to non-cancer cell cultures." (PMID 29273857, 2018). "On cancer characteristic, inhibition Notch could decrease the proliferation through downregulation of oncogene c-Myc and Cyclin D1." (PMID 29721169, 2018). "However, immunoblotting detection of cyclin D1 concurrent with the evaluation of cell cycle arrest needed to approve the effect of SKE on cancer treatment." (PMID 29755565, 2018). "In this article, we found that bufadienolides could inhibit proliferation of cancer cells via arresting cancer cell cycle in G1 phase, which resulted from the decreased expression of cyclin D1 and Rb phosphorylation." (PMID 30108651, 2018). "Metformin has been shown to block cyclin D1, Cdk4 and Cdk6 in various cancers." (PMID 29765528, 2018). "Indeed, proteasomal degradation has been viewed as an important regulator of cyclin D1 levels in cancer cells and many cancer therapeutic agents exerts anti-proliferative activity through cyclin D1 proteasomal degradation." (PMID 29925351, 2018). "Therefore, the drugs helping to reduce the expression of cyclin D1 in cancer cells will have a significant impact on the intracellular processes of cancer and can be useful in treatment and prevention of cancer." (PMID 29755565, 2018). "Thus, induction of cyclin D1 degradation has been regarded as one of the potential anti-cancer targets." (PMID 29554905, 2018). "Moreover, through its effects on aerobic glycolysis, ALDOA is able to alter the microenvironment of cancer and thus impair the regulation of cyclin D1 transcription." (PMID 29764507, 2018). "The high expression level of CCND1 mRNA was correlated with the BRAF-like cancer (p < 0.001)." (PMID 30428594, 2018). "The present meta-analysis, contained a total of 12 studies comprising 1791 cancer cases and 1948 controls showed the lack of significant association between CCND1 G870A polymorphism (rs9344) and overall cancer risk in all the genetic models." (PMID 30361291, 2018). "In addition, nuclear factor-kappa B (NF-κB) has also been involved with cancer biology through regulation of proliferation factors such as CCND1." (PMID 28445979, 2017). "Tumor suppressor APC is lost in 85% of CRCs, leading to β-catenin stabilization, activation of Wnt targets such as c-Myc (Myc) and cyclin D1 and cancer initiation, which cooperates with hyperactivated RAS/RAF/ERK, and PI3K/AKT/mTOR signaling in cancer progression." (PMID 28030835, 2017).
cancer (continued). "Our results suggest that DKC-E70 may downregulate cyclin D1 as one of the potential anti-cancer targets through cyclin D1 degradation by T286 phosphorylation dependent on ERK1/2, p38 or GSK3β, and cyclin D1 transcriptional inhibition through Wnt signaling." (PMID 28870200, 2017). "Taken together, our results suggest that MCM7–cyclin D1 pathway may participate in cancer progression and serve as a biomarker for prognosis in HCC." (PMID 28182015, 2017). "As key regulators of the G1 progression step within the cell cycle, cyclin D1 may play a pivotal role in the process of carcinogenesis and cancer progression." (PMID 28938543, 2017). "As we know, CCND1 has been considered to be a cancer gene which could regulate progression from the G1 phase of the cell cycle to the S phase." (PMID 29049220, 2017). "Aberrant cyclin D1 expression has been reported in many human cancers." (PMID 29118671, 2017). "However, it is noteworthy that cyclin D1 protein levels in the SLC7A11-AS1low cancer tissues were higher than those in the SLC7A11-AS1high cancer tissues." (PMID 29348845, 2017). "Cyclin D1 was reported to be a key element in cell proliferation in many types of cancers." (PMID 28558682, 2017). "This important finding and the selective impairment of the interaction between La and Bcl2 and CCND1 mRNAs, suggests that the compounds might target La-supported cancer cell promoting processes." (PMID 28291789, 2017). "We reported that the levels of cyclin D1 were decreased following cancer cells treatment with hESCs-CM, and this could have helped keeping RB hypophosphorylated thus preventing G1/S phase transition." (PMID 28068409, 2017). "Whereas Shimura's study indicated that IR could activate AKT/GSK3β/cyclin D1 pathway resulting in cancer cell enhanced proliferation and radioresistance." (PMID 28061440, 2017). "It has been also reported that metformin may have beneficial effects on the prevention and treatment of cancer as it inhibits the proliferation and cyclin D1 expression of diverse cultured cancer cells." (PMID 28859084, 2017). "In highly resistant spherical cancer cells, which results from enhanced self-renewal via cyclin D1 and cyclin D1-dependent activation of Smad2/3 and Smad4, inducing differentiation with Smad inhibitor is a critical tactic for turning resistant CSCs into therapy-sensitive cells." (PMID 28415588, 2017). "Identical to the role of CREPT in other carcinomas, such enhancement may be also fulfilled through the activation of cyclin D1 and c-Myc." (PMID 28369091, 2017). "In addition to its role in normal proliferation, cyclin D1 is one of the most frequently over-expressed oncogenes in human cancers, and abundant literature has demonstrated that it can play an important role in cancer development." (PMID 27351284, 2016). "Previous studies show that NR4A1 acts as a coactivator of genes with GC-rich promoters (pathway 3) that play a role in cancer cell proliferation and survival, and these include survivin, bcl-2, cyclin D1, epidermal growth factor receptor (EGFR) and the oncogene cMyc." (PMID 27144436, 2016). "The overexpression of cyclin D1 alters cell cycle progression, which may contribute to tumorigenesis; indeed, cyclin D1 overexpression has been observed in various cancers." (PMID 26506239, 2016). "Furthermore, cyclin D1 regulates metalloproteinase (MMPs), traditionallyassociated with matrix remodeling, cancer invasion and with angiogenesis." (PMID 26689991, 2016). "CCND1 can be used as a therapeutic target in cancer therapy." (PMID 27148394, 2016).
cancer (continued). "In addition, we further showed that increase in miR-329 expression was associated with a decrease in oncogene cyclin D1, cyclin D2, and an increase in p57 and p21. cyclin D1 and cyclin D2 are well-established oncogenes in many different cancers." (PMID 26909600, 2016). "Somatic mutations of CCND1 are not a frequent alteration in cancer, and, in particular have not been reported in BC." (PMID 27765917, 2016). "A growing body of cancer research evidence has indicated that activation of gp130/STAT3 induces the expression of multiple survival, proliferation and antiapoptosis associated genes, such as MCL-1, Bcl-2, Bcl-XL, Survivin and cyclin D1." (PMID 27537522, 2016). "Cyclin D1 (Ccnd1) is among the 10 proto-oncogenes most frequently amplified in cancer." (PMID 27105504, 2016). "In the pan-cancer FFLs, two genes, CCND1 and JUN, are drug targets of ATO." (PMID 26655252, 2016). "Similarly, the DSG3-plakoglobin-TCF/LEF-Myc/cyclin D1/MMP signaling pathway facilitates cancer growth and invasion." (PMID 26933815, 2016). "However, in both hepatocytes and the cancer cell lines examined here, cyclin D1 represses PPARα activity and FA oxidation." (PMID 27351284, 2016). "To examine whether cyclin D1 may regulate PPARα-mediated metabolism in malignant cells, we tested a number of different cancer cell lines." (PMID 27351284, 2016). "Our results suggest that miR-495 could regulate the protein levels of Foxo1, p27kip1, p21Cip1, and Cyclin D1, all of these genes are downstream of Akt1, and subsequently inhibit cancer cell growth by promoting cell cycle arrest." (PMID 27323412, 2016). "Significantly, individual types of cancer typically associate with particular lesions in this network (e.g., mutation of RB1 in retinoblastoma, mutation of INK4A in pancreatic cancer, amplification of Cyclin D1 in breast tumors, etc.)." (PMID 27401552, 2016). "In addition, cyclin D1 and survivin have been identified as two key transcriptional targets of the Wnt/β-catenin pathway, and are critical for cancer cell proliferation and cell death." (PMID 26820295, 2016). "Thus, it has been accepted that cyclin D1 has been an attractive chemopreventive and therapeutic target for anti-cancer development." (PMID 27670681, 2016). "Aberrant activation of STAT3 signaling participates in the initiation, development and progression of human cancers via induction of STAT3 downstream genes that encode antiapoptotic proteins, cell cycle regulators and angiogenic factors such as Bcl-2, Cyclin D1 and VEGF." (PMID 27317769, 2016). "We investigated whether the induction of cyclin D1 attenuated the response to Nutlin-3 in these cancer cells." (PMID 27129163, 2016). "Notably, expression of MDM2-A and MDM2-B increases the expression levels of cyclin D1, which has an oncogenic role in cancer cells." (PMID 27129163, 2016). "This study demonstrates that TMPRSS4 modulates both invasion and proliferation via Slug and cyclin D1, which is a previously unrecognized pathway that may regulate metastasis and cancer progression." (PMID 27385093, 2016). "We evaluate the expression of MDM2-FL, MDM2-A and cyclin D1 in different cancer cell lines." (PMID 27129163, 2016). "Interestingly, studies in mouse retinal tissue and mouse cancer lines have shown that Cyclin D1 can participate in transcriptional regulation." (PMID 26883361, 2016). "Interestingly, PD2 overexpression also resulted in enrichment of cancer stem cells (CSCs) and upregulation of oncogenes such as c-Myc and cell cycle progression marker, cyclin D1." (PMID 26689992, 2016). "However, many in vitro and in vivo studies have shown that the overexpression of Cyclin D1 enhances cell proliferation, and Cyclin D1 plays an important oncogenic role in many cancers." (PMID 27929439, 2016). "In addition, it has been suggested that expression of Cdx1 reduces cancer cell proliferation by reducing cyclin D1 expression." (PMID 27092172, 2016).
cancer (continued). "Moreover, we propose that subcellular localization of Ccnd1 is an interesting guideline to measure cancer outcome." (PMID 27105504, 2016). "For example, cyclin D1, which enhances transcriptional regulation in several human cancers, promotes progression through the G1-S phase of the cell cycle by binding to CDK-4 to phosphorylate and inactivate retinoblastoma protein and release E2F transcription factors." (PMID 27811358, 2016). "Given the current interest in identifying potential metabolic targets in cancer, further study of the cyclin D1-PPARα regulatory interaction may provide insight into rationally-designed treatment strategies." (PMID 27351284, 2016). "It is likely that cross-regulation between cyclin D1 and Dicer might occur in other cancers, especially in ATC, which are enriched in SOX2 producing cells, which we suggest is part of the network." (PMID 25705224, 2015). "Cyclin D1 is a major oncogene overexpressed in many types of cancers." (PMID 26078811, 2015). "In the context of cancer biology, only a limited number of Kaiso target genes have been identified thus far, including the matrix metalloproteinase matrilysin (MMP7), metastasis-associated gene 2 (MTA2), cyclin D1 (CCND1) and Wnt11 (WNT11)." (PMID 25713299, 2015). "NF-κB is a sequence specific transcription factor that regulates expression of many cellular genes such as genes involved in cancer cell survival (Mcl-1), proliferation (C-myc, Cyclin D1), and invasion (matrix metalloproteinase MMP-9), which play important roles in carcinogenesis." (PMID 25875501, 2015). "Expression of cyclin D1, a G1/S transition protein has been shown in several types of cancers." (PMID 25837691, 2015). "Moreover, cyclin D1 is overexpressed in human cancers, including malignant hemopathies, after genetic alterations, such as chromosomal translocation, but also in the absence of any detectable genetic alteration." (PMID 25881299, 2015). "In the present study, resibufogenin down-regulated cyclin D1 through the proteasomal degradation, thereby suggesting that resibufogenin might be useful for the treatment of malignant tumors with over-expression of cyclin D1." (PMID 26121043, 2015). "To study, whether PTEN deletion has an additional prognostic value in cancers harboring co-amplification of HER2, MYC, or CCND1, we stratified cancers for survival analysis according to the status of PTEN and HER2, PTEN and MYC, as well as PTEN and CCND1." (PMID 26672755, 2015). "For the first time, we provide evidence that let-7 and cyclin D1 form a feedback loop in regulating therapy response of cancer cells and cancer stem cells, and importantly, that alteration of let-7 expression, mainly caused by cyclin D1, is a sensitive indicator for better chemotherapies response." (PMID 25702703, 2015). "Therefore, CCND1 is considered as an attractive target for anti-cancer therapy, with several agents currently in development." (PMID 26172301, 2015). "The increased expression of Cyclin D1 and Cyclin B1 can promote the cell transformation during the G1/S and G2/M phases, respectively, which enhances the cell proliferation level, and consequently leads to the occurrence of cancer." (PMID 25950458, 2015). "Reduced cyclin D1 expression in BRCA1 basal cancers may, in part, be due to the inhibition of translation mediated by mir-576-3p, mir-1826 and mir-638." (PMID 26152113, 2015). "Therefore, cyclin D1 is important in G1 to S-phase transition, and is over-expressed in many human malignant tumors." (PMID 26121043, 2015). "Many miRNAs regulate expression of cyclin D1 in various cancer cells." (PMID 25971210, 2015).
cancer (continued). "In the present study, GO-Y031 targeted both β-catenin and STAT3, which are transcriptional regulators that control various downstream molecules, such as c-Myc, cyclin D1, vascular endothelial growth factor, and survivine, and contribute to cancer cell growth and survival." (PMID 25331984, 2015). "Nevertheless, our findings suggest immunohistochemistry for FOXP1/NRP1/cyclin D1 may be useful, in conjunction with family history, in selecting patients with basal cancers for BRCA1 screening." (PMID 26152113, 2015). "Since Cyclin D1 has been recently found promoting metastasis of cancer cells, we wondered whether its expression mediate the anti-metastasis effect of miR-195 in OS." (PMID 25823925, 2015). "We chose ERK, TGFB1, TGFB2, SIRT1, IL-6, PI3K, and WHSC1 (which were controlled by several genes) and three other genes AR, BCL-XL, and CCND1 that could mark the deterioration of the cancer, for testing." (PMID 26603105, 2015). "LY294002 (PI3K inhibitor) could inhibit cancer cell proliferation and induce G1 arrest, accompanied by reduced cyclin D1 and CDK4 levels." (PMID 26592552, 2015). "Cyclin D1 and CDKs are considered as therapeutic targets for cancer to suppress its growth." (PMID 26592552, 2015). "In addition to regulating the cell cycle, Cyclin D1 is a well-known oncogene that is frequently overexpressed in various cancer cells." (PMID 25971210, 2015). "The overexpression of CCND1 is one of the most frequently observed changes in various cancer types." (PMID 26317630, 2015). "For instance, quite recently TRα was found to enhance cancer cell migration and metastasis via inhibition of miR-17 as well as to maintain pro-neoplastic potency by interacting with the cyclin D1/CDK/Rb/E2F cascade, the wnt pathway or by inducing CTNNB1 gene expression." (PMID 26029931, 2015). "First, one target of miR-503 is cyclin D1, which can promote cancer cell growth." (PMID 24944699, 2014). "For example, GTT down-regulates cyclin D1 and cyclin E levels in several cancer cell lines." (PMID 24980711, 2014). "It has been reported that overexpression of CDK4/6 and CCND1 and deregulated E2F could contribute to cancer progression." (PMID 24826192, 2014). "However, the ORAOV1 gene was identified within chromosomal band 11q13, which includes several known cancer-related genes such as CCND1, FGF4, FGF3, and CTTN." (PMID 24930674, 2014). "Given the role of cyclin D1 to promote the cell cycle it was surprising that frst, the amplifcation of the cyclin D1 locus is rarely observed in cancers with over expression of cyclin D1 and that second, the enforced over expression of cyclin D1 is not the transforming property of cyclin D1." (PMID 24429466, 2014). "Targeting cyclin D1 could hinder progress toward advanced cancer because cyclin D1 levels increase in the relatively early stages of tumorigenesis." (PMID 24618206, 2014). "Deregulation of Cdk4 and cyclin D1 is widespread in human cancer." (PMID 24606538, 2014). "Furthermore, the weight of Virus_CCND1-derived cancer was decreased by comparison with Saline and Virus_Scramble." (PMID 24618206, 2014).